RELA (RELA proto-oncogene, NF-kB subunit)
Diseases named in the same sentence as RELA in open-access papers (continued):
Sharing a sentence is not in itself a finding about the gene and the disease.
ependymoma (continued). "By DNA methylation profiling, tumors with MN1 or RELA rearrangement clustered with high-grade neuroepithelial tumor with MN1 alteration (HGNET-MN1) and RELA-fusion ependymoma, respectively." (PMID 30876455, 2019). "The concordance between p65‐RelA IHC and DNA methylation assay for the detection of the RELA‐fused ependymomas was high, with 96.4% agreement (κ = 0.916; CI95[0.754‐1])." (PMID 30325077, 2019). "As a result, out of 29 histologically verified ST-EPNs a total of 20 (68.9%) were identified as RELA fusion-positive ependymomas." (PMID 30514397, 2018). "More recently, it was shown that RELA fusion genes drive ST-ependymoma formation from periventricular neural stem cells in mice and the RELA-fusin-induced tumorigenesis was dependent on NF-kB and also from other signaling pathways." (PMID 30279357, 2018). "EPN_RELPOS and EPN_YAP1 ependymomas were characterized by recently discovered fusion genes involving RELA and YAP1 respectively." (PMID 30559935, 2018). "Recently, the fusion oncogene RELA-C11orf95, leading to constitutively active NF-kappaB signalling, was identified as a centrally important molecular driver event in supratentorial ependymomas." (PMID 27556362, 2016). "We considered whether this evolution was directed and reproducible and analyzed the copy number profiles of three independently propagated tumor lines of the same RELA-driven ependymoma model." (PMID 41381884, 2026). "Firstly, studies have shown that these tumors have the occurrence of v-relavian reticuloendotheliosis viral oncogene homolog A (RELA) fusion, a genetic modification characterized by the involvement of the RELA gene, which is a commonly observed phenomenon in supratentorial ependymomas." (PMID 38807869, 2024). "In addition, supratentorial ependymomas most commonly harbored the C11orf95 – RELA fusion (71% of tumors, also known as ZFTA-RELA) and meningiomas most frequently harbored fusions in NF2 and YAP1 (both 15% of tumors)." (PMID 36711972, 2023). "Notably, all RELA‐altered ependymomas were successfully classified by the methylation‐based classification." (PMID 35892159, 2022). "The final pathological diagnosis was RELA fusion-positive ependymoma, WHO grade III." (PMID 35986385, 2022). "Together with our results, L1CAM expression may be more related to C11orf95 than to RELA in ST ependymomas and ELTMDs with fusion genes involving C11orf95." (PMID 33576087, 2021). "By elucidating core transcriptional regulatory circuitries from the set of gained enhancers, we identified several key TFs, including RXRA, NFE2L2, IRF2, RELA, etc., involved in cell growth and migration, some of which were also revealed to have tumor-promoting functions in ependymoma and RCC25,26." (PMID 34294701, 2021). "Notably, among nine ependymoma patients with the RELA+ signature, eight survived at least 5 years after diagnosis." (PMID 34314101, 2021). "To further dissect the molecular mechanism of RELAFUS-driven ependymoma formation, we examined the implication of RELA target genes in the RELAFUS1 transcription network using publicly available Rela ChIP-seq data in murine embryonic fibroblasts (MEFs) after TNF stimulation." (PMID 33685520, 2021). "Besides ependymomas with RELA fusion, tumors with YAP1-MAMLD1 fusion were described as a second entity emerging in the supratentorial compartment of pediatric patients." (PMID 33481105, 2021). "In childhood ependymomas, CDKN2A deletion is restricted to ependymomas with RELA fusion." (PMID 34008056, 2021). "We present results here showing that contrary to the hypothesis that C11orf95-RELA ependymoma is driven by the RELA component of the fusion, binding affinity of the fusion protein to DNA is dictated by the C11orf95 component." (PMID 32909151, 2020).
ependymoma (continued). "The two main subgroups of supratentorial ependymomas are characterized by fusions on chromosome 11 involving the coactivator RELA (nuclear factor NF-kappa-B p65 subunit) (affecting older children) or less frequently YAP1 fusions (affecting children <3 years of age)." (PMID 32103286, 2020). "DNA methylation profiling helped in the differential diagnosis of RELA‐fused ependymomas." (PMID 30325077, 2019). "In this context, it is of paramount importance to validate additional tools to identify different ependymoma subtypes that are applicable and available for routine diagnosis and clinical practice, in particular for the diagnostics of RELA fusion‐positive ependymomas." (PMID 30325077, 2019). "RELA fusions and loss of CDKN2A have been routinely observed in aggressive ependymomas." (PMID 28468611, 2017). "However, the L1CAM protein expression in large sample gliomas other than ependymoma, its relationship with the RELA gene and its prognostic significance remained unknown." (PMID 32509846, 2020). "Ependymoma with RELA fusion has been defined as a novel entity of the revised World Health Organization 2016 classification of tumors of the central nervous system (CNS), characterized by fusion transcripts of the RELA gene and consequent pathological activation of the NFkB pathway." (PMID 30325077, 2019). "Supratentorial ependymomas are made up of ST-sub-ependymoma and two subgroups, defined by characteristic oncogenic fusions (YAP1 and RELA)." (PMID 35745584, 2022). "Supratentorial (ST) ependymomas in children have two major subgroups: RELA fusion-positive ependymoma and YAP1 fusion-positive ependymoma." (PMID 35706426, 2022). "ST-EPN-RELA usually harbors the fusion protein of C11orf95 and RELA and, in ST-EPN-YAP1 ependymoma, the transcriptional coactivator YAP1 fuses with other genes such as MAMLD1 and FAM118B, resulting in the upregulation of tumor promoting signaling pathways." (PMID 35884462, 2022). "Clustering analysis, including one RELA+ and one YAP1+ ependymoma for comparison, revealed one PNET sample displaying clear expression of RELA+ signature genes." (PMID 34314101, 2021). "Here, we report hitherto histopathologically unclassifiable high‐grade tumors, under the tentative label of “ependymoma‐like tumors with mesenchymal differentiation (ELTMDs),” harboring C11orf95‐NCOA1/2 or ‐RELA fusion." (PMID 33576087, 2021). "RELA and ZFTA transcript levels were upregulated in ZFTA:RELA-fused ependymomas (adjusted p = 1.03e − 61 and adjusted p = 1.10e − 19, respectively)." (PMID 34355256, 2021). "The RELA+ and YAP1+ marker probes hybridised to supratentorial tumours, while the PFA, PFA1, PFA2, and PFB marker probes hybridised to PF ependymomas." (PMID 34314101, 2021). "Supratentorial ependymomas are characterized by mutually exclusive recurrent RELA and YAP1-related gene fusions, thereby being segregated into two subgroups denoted as ST-EPN-RELA and YAP1." (PMID 33685520, 2021). "Since a high proportion of supratentorial ependymomas are driven by gene fusions involving ZFTA (C11orf95, most frequently fused to RELA) or YAP1, we performed mRNA sequencing of all samples with sufficient material (n = 20)." (PMID 34355256, 2021). "Cellular ependymoma is a term that has disappeared from the new WHO 2016 standard and is classified as either classical or anaplastic or as belonging to the RELA fusion-positive subtype." (PMID 34203272, 2021). "In eight ependymomas and one PNET, which all showed the RELA+ NanoString signature, we detected the presence of the ZFTA‐RELA fusion transcript." (PMID 34314101, 2021).
ependymoma (continued). "Within the supratentorial compartment, two molecularly defined types of ependymoma are characterized by recurrent gene fusions, one involving the gene ZFTA (formerly referred to as C11orf95, most frequently fused to RELA), and the other involving YAP1." (PMID 34355256, 2021). "Therefore, CDKN2A inactivation in RELA-ependymomas may represent a potential therapeutical target." (PMID 32514758, 2020). "For this we used a list of genes that was previously established to be differentially expressed between YAP1-MAMLD1 fusion and RELA fusion-positive human ependymoma subtypes, as well as between YAP1-MAMLD1 and C11orf95-RELA-driven mouse ependymoma models." (PMID 32404936, 2020). "To conclude, IHC for nuclear p65‐RelA and FISH using break‐apart probes are highly valuable tools to diagnose RELA‐fused ependymomas, which show a worse outcome than ependymomas with YAP1 fusions and mixed ependymomas/subependymomas." (PMID 30325077, 2019). "A combination of RT-PCR, FISH, and RNA sequencing identified RELA fusion in 19 of 29 histologically verified ST-EPN cases, whereas another case was diagnosed as ependymoma RELA fusion-positive via the methylation classifier (68.9%)." (PMID 30514397, 2018). "In the supratentorial location, ependymomas with the presence of a fusion gene between C11ORF95 and RELA (ST-EPN-RELA) have a poor prognosis, and in the posterior fossa location the ependymoma group PF-EPN-A is characterised by a poor prognosis." (PMID 29098416, 2018). "Recently, one genetically defined ependymoma subtype has been added to the 2016 CNS WHO as a novel entity: Ependymoma, RELA fusion-positive." (PMID 28320419, 2017). "More than 70% of supratentorial ependymomas are characterized by fusions between C11ORF95 and the RELA gene, and were recently termed ST-EPN-RELA." (PMID 27858204, 2017). "Supratentorial ependymomas are classified through ZFTA, previously known as RELA, or YAP1 fusions." (PMID 40677455, 2025). "However, predicting patient outcomes based solely on histological or molecular markers, especially distinguishing RELA fusion‐positive (II/III) and anaplastic (III) ependymomas, remains complex." (PMID 39777089, 2024). "ZFTA is the current term used for C11orf95 gene, which is said to be more representative of this type of ependymoma than v-rel reticuloendotheliosis viral oncogene homolog A (RELA), as ZFTA may fuse with genes other than RELA." (PMID 38966175, 2024). "Among PF ependymomas, 9 had global loss of H3K27me3, whereas amongst ST, 1 had YAP1 fusion and other, negative L1CAM and p65/RELA on immunohistochemistry." (PMID 36721481, 2023). "Ependymoma, RELA fusion-positive (EPN-RELA) was newly proposed in the WHO Classification of Tumours of the Central Nervous System (CNS), 2016 updated fourth edition (CNS4) as an ependymoma (EPN) with a C11orf95-RELA fusion gene typically occurring in the supratentorial compartment." (PMID 37322295, 2023). "This modification reinforces the idea that supratentorial-ependymomas exhibiting fusion that implicates the C11orf95 (now called ZFTA) gene with or without the RELA gene, represent the same histomolecular entity." (PMID 34389065, 2021). "Molecular classification using anatomical compartments and the DNA methylation profile newly classifies ependymomas including the myxopapillary ependymoma (MPE), the subependymoma (SE), the (anaplastic) ependymoma (EPN), and the RELA fusion-positive ependymoma (EPN-RELA)." (PMID 34203272, 2021). "The RELA fusion ependymoma, named ST-EPN-RELA, is the result of a fusion between the chromosome 11 open reading frame (C11ORF95) and the v-rel avian reticuloendotheliosis viral oncogene homolog A (RELA)." (PMID 34203272, 2021). "Opposed to this model, recent publications described supratentorial ependymomas lacking RELA or YAP1 fusions." (PMID 33481105, 2021). "The four RELA/YAP1 fusion‐negative ependymoma patients varied in terms of age (1–17 years old) and treatment." (PMID 34314101, 2021).
ependymoma (continued). "In the RELA-like group histologically assigned to WHO grade III and resembling RELA-fused ependymomas, tumors lacked nuclear expression of p65-RelA as a surrogate marker for a pathological activation of the NF-κB pathway." (PMID 33481105, 2021). "They found that infiltrating T-cells in RELA fusion supratentorial ependymoma did not secrete IFN-gamma." (PMID 32075140, 2020). "In summary, L1CAM was found to be a significant marker in predicting the prognosis of glioma patients, but unlike ependymoma, it was not correlated with RELA in other gliomas." (PMID 32509846, 2020). "IHC positivity for YAP1 protein was observed in YAP‐fused ependymomas as well as in RELA‐fused ependymomas and did not allow to distinguish these two subgroups (data not shown)." (PMID 30325077, 2019). "Histopathological and molecular profile of ependymomas without evidence of RELA‐C11orf or YAP1 fusion." (PMID 30325077, 2019). "Thirty‐four out of 40 (85%) cases were confirmed by integrated diagnoses as ependymal tumors, including 22 RELA‐fused ependymomas (71% of ependymal tumors), two YAP1‐fused ependymomas (6%), six non‐RELA/non‐YAP1 ependymomas (18%) and four ependymal/subependymal mixed tumors (12%)." (PMID 30325077, 2019). "In addition, data regarding the molecular subtype (i.e. RELA and/or YAP1 fusion) of these ependymoma samples was unavailable for the majority of cases as physicians rarely requested this specific testing." (PMID 29487694, 2018). "The ST-EPN-RELA subgroup can be identified by immunostaining for the surrogate markers L1 cell adhesion molecule (L1CAM) or anti-NFkB (p65, RelA), the latter based on the discovery that C11orf95–RELA fusions drive oncogenic NF-kB signalling in ependymoma." (PMID 29098416, 2018). "Taking into account the major subtypes of ependymomas in each location, ie RELA-fusion positive or negative supratentorial tumors and PFA or PFB tumors, would also be of importance." (PMID 28617804, 2017). "RELA fusion positive had been considered as a negative prognostic factor in ependymomas." (PMID 32974195, 2020). "Nonetheless, it is important to be aware that histologically diagnosed RELA-fusion negative ependymomas may have a biology which is different from that of quintessential RELA-fusion positive ependymomas." (PMID 30514397, 2018). "No consensus was made upon morphologically diagnosed ST-ependymomas without RELA/YAP1 fusion." (PMID 27858204, 2017). "However, the pathogenesis of RELA fusion-negative ependymomas remains elusive." (PMID 30514397, 2018). "Of all supratentorial ependymomas in children diagnosed between 2003 and 2017 at the DGNN brain tumor reference center, approximately 15% harbored neither a RELA nor a YAP fusion." (PMID 33481105, 2021). "The remaining eight tumours lacking a RELA or YAP1 fusion presented as a heterogenous cohort, supporting our findings that paediatric ependymomas include tumours that can be classified as RELA/YAP1 fusion‐negative." (PMID 34314101, 2021). "One probe for the DRD1 gene exhibited uniform low hybridisation across all ependymoma samples, and a probe for ANGTPL6 showed high expression in both RELA fusion‐positive and RELA fusion‐negative reference samples." (PMID 34314101, 2021). "From a clinical perspective, further research is required to assess the impact of ZFTA‐RELA and other fusions on patient survival, as well as the clinical and biological heterogeneity among RELA/YAP1 fusion‐negative and PFA ependymomas." (PMID 34314101, 2021). "In one ependymoma that exhibited the RELA+ signature, but low RELA expression at the RNA level, we did not detect the ZFTA‐RELA fusion transcript." (PMID 34314101, 2021). "Our series is the first to extensively characterize this new subset of supratentorial ZFTA-fused ependymomas and highlights the usefulness of ZFTA FISH analysis to confirm the existence of a rearrangement without RELA abnormality." (PMID 34389065, 2021).
ependymoma (continued). "We detected nine RELA+, one YAP1+, and four not molecularly classified ependymomas." (PMID 34314101, 2021). "Therefore, we designated nine samples from cluster 1 as RELA+, six samples from cluster 2 as not classified (NC), and one sample as YAP1+ ependymoma." (PMID 34314101, 2021). "Furthermore, expression of wild type RELA or activating RELA mutants failed to induce brain tumor formation in mice, strongly suggesting an important role of non-NF-κB pathways in the RELAFUS-driven ependymoma formation." (PMID 33685520, 2021).